GLI1 (GLI family zinc finger 1)
Diseases named in the same sentence as GLI1 in open-access papers (continued):
Sharing a sentence is not in itself a finding about the gene and the disease.
Peritoneal Fibrosis (1 paper, 2025). Disorder characterized by a wide range of structural changes in PERITONEUM, resulting from fibrogenic or inflammatory processes. "Similarly, the potential involvement of Gli1 in peritoneal fibrosis, which has been linked to Hedgehog signalling and fibroblast activation in other tissues, warrants further exploration in this context." (PMID 40133213, 2025). "f/fYAP; Gli1‐CreERT2+/− mice were intraperitoneally administered tamoxifen or the same volume of corn oil before the induction of peritoneal fibrosis." (PMID 40133213, 2025). "Further translational studies are needed to clarify the therapeutic effects of targeting Gli1‐specific YAP expression on peritoneal fibrosis or EPS." (PMID 40133213, 2025). "Our results demonstrate the essential role of YAP in activated Gli1+ myofibroblasts and the development of peritoneal fibrosis." (PMID 40133213, 2025). "After the induction of peritoneal fibrosis, these Gli1+ cells expressed α‐SMA, suggesting that these cells were activated by PDF and transdifferentiated into myofibroblasts." (PMID 40133213, 2025). "Confocal immunofluorescence microscopy revealed that Gli1 colocalized with activated myofibroblasts expressing α‐SMA after the induction of peritoneal fibrosis." (PMID 40133213, 2025). "Moreover, YAP was partially expressed in peritoneal Gli1‐expressing cells in mice with peritoneal fibrosis." (PMID 40133213, 2025). "Moreover, depleting YAP expression in Gli1‐expressing cells or verteporfin treatment reduced the severity of the peritoneal fibrosis induced by PDF." (PMID 40133213, 2025). "In addition, the population of Gli1+ cells in the peritoneum was increased by the induction of peritoneal fibrosis." (PMID 40133213, 2025). "Depleting YAP in Gli1+ cells inhibits FMT and the development of PDF‐induced peritoneal fibrosis and angiogenesis." (PMID 40133213, 2025). "However, the role of YAP and whether Gli1‐expressing cells in the peritoneum contribute to myofibroblast differentiation in peritoneal fibrosis has not been thoroughly investigated." (PMID 40133213, 2025).
pilocytic astrocytoma (1 paper, 2017). Pilocytic astrocytoma is a rare subtype of low-grade glioma of the central nervous system characterized by a well circumscribed, often cystic, brain tumor with a discrete mural nodule and long, hair-like projections that extend from the neoplastic astrocytes. "The GLI1 expression was significantly upregulated in GBMs in comparison to pilocytic astrocytomas and normal brains." (PMID 28030801, 2017).
pleural neoplasm (1 paper, 2026). A benign or malignant neoplasm that involves the serous membrane that lines the lungs and thoracic cavity. "This case expands the anatomic spectrum of GLI1-altered tumors and underscores the value of molecular testing in distinguishing them from other pleural neoplasms." (PMID 41888999, 2026).
polyposis (1 paper, 2023). "Here, we demonstrate that Alk3 or Smad4 KO in Gli1+ cells results in tumefaction, cavity formation, and polyposis development in the large intestine." (PMID 37889976, 2023).
primary effusion lymphoma (1 paper, 2021). A large B-cell lymphoma located in the body cavities, characterized by pleural, peritoneal, and pericardial fluid lymphomatous effusions and that is always associated with human herpes virus-8 (HHV-8). "A recent study from our lab reported the increased expression of GLI1 in KSHV infected primary effusion lymphoma (PEL) cells." (PMID 33494284, 2021).
pulmonary hypertension (1 paper, 2025). Increased pressure within the pulmonary circulation due to lung or heart disorder. "Gli1+ cells recruit and contribute to vascular muscularization in pulmonary hypertension induced by hypoxia, thus selective ablation of Gli1+ cells significantly alleviate vascular remodeling." (PMID 40750730, 2025). "In addition to their differentiation ability, Gli1+ cells stimulate VSMCs induce hypoxia-induced pulmonary hypertension." (PMID 40750730, 2025).
solitary fibrous tumor (1 paper, 2023). Solitary fibrous tumor (SFT) represents a diverse group of ubiquitous rare spindle cell neoplasms that may be benign or malignant and that most frequently arises from the pleura and peritoneum and rarely from other sites such as head and neck, liver and skeletal muscle. "These authors noted the importance of nuclear staining for GLI1 and STAT6 for differential diagnosis with GLI tumors and solitary fibrous tumors, which can share similar locations and morphology." (PMID 37108696, 2023).
solitary median maxillary central incisor syndrome (1 paper, 2021). A hereditary autosomal dominant condition characterized primarily by single (unpaired) deciduous and permanent maxillary central incisors and short stature. "This is consistent with the clinical finding that RME treatment shows no expansion effect on midpalatal sutures in patients with solitary median maxillary central incisor syndrome (SMMCI), which was proven to be caused by a mutation in the SHH gene upstream of Gli1." (PMID 34434241, 2021).
spinal chordoma (1 paper, 2019). A slow-growing malignant bone tumor arising from the remnants of the notochord and occurring in the spine. "The results of the in situ hybridization in our study were partially positive for PTCH1 and GLI1 in primary conventional cranial and spinal chordoma." (PMID 30769952, 2019). "Due to the strong expression of Shh and Gli1 in the tumor cells, canonical activation of Shh pathway is likely to be possible in cranial and spinal chordomas and its recurrence." (PMID 30769952, 2019). "In addition, 18 (100%) spinal chordomas, including twelve primary tumors and six first relapses, from six patients were immunohistochemically examined for the expression levels of Shh and GLI1." (PMID 30769952, 2019).
spinal muscular atrophy (1 paper, 2020). A motor neuron disease that affect the muscles, and characterized by muscle weakness and atrophy resulting from progressive degeneration and irreversible loss of the anterior horn cells in the spinal cord (i.e., lower motor neurons) and the brain stem nuclei. "Expression data mining of ALS and spinal muscular atrophy (SMA) motor neurons shows reduced CRABP1, coincided with reduction in Shh-Gli1 signaling components." (PMID 32527063, 2020).
spindle cell sarcoma (1 paper, 2024). A malignant mesenchymal neoplasm composed of spindle-shaped cells. "Nevertheless, according to our results, GLI1, NKX2.2, and BCOR can also be expressed in SSs, representing a challenge in differential diagnosis with other small round/spindle cell sarcomas." (PMID 39062853, 2024).
steatosis (1 paper, 2016). Increased lipid within the cytoplasm of cells. "Using transgenic mice with conditional hepatocyte-specific deletion of Smoothened in adult mice, we showed that hepatocellular inhibition of Hedgehog signaling leads to steatosis by altering the abundance of the transcription factors GLI1 and GLI3." (PMID 27185526, 2016). "Ad (iii), to proof the assumption that reversal of the level of the Gli TFs (GLI1 and GLI3) is able to overcome steatosis we treated isolated hepatocytes from steatotic ob/ob mice with overexpression plasmids for GLI1, GLI2, GLI3 and a combination of GLI1 and GLI3." (PMID 27185526, 2016). "Furthermore, the obvious down-regulation of Gli1 and Gli3 in human livers with steatosis supports the universality of the postulated 'steatotic Gli-code' and reveals new insights in the regulation of hepatic lipid metabolism." (PMID 27185526, 2016). "However, the combination of GLI1 and GLI3 significantly mitigated the steatosis in the hepatocytes from ob/ob mice indicating that parallel changes in both GLI factors are required to reverse steatosis." (PMID 27185526, 2016).
systemic lupus erythematosus (1 paper, 2022). An autoimmune multi-organ disease typically associated with vasculopathy and autoantibody production. "We find suggestive, under-characterized TFs, such as RUNX3 in mesoderm development and GLI1 in systemic lupus erythematosus." (PMID 36040971, 2022).
tendinopathy (1 paper, 2017). "To elucidate the relevance of Hh signaling activation in human tendon injury, we also examined the expression of GLI1 and MKX in human tendinopathy specimens." (PMID 29244023, 2017). "Furthermore, co-localization of GLI1+ and MKX+ cells is also found in human tendinopathy specimens." (PMID 29244023, 2017).
urinary bladder tumors (1 paper, 2023). "It was also found that low-grade urinary bladder tumors were more likely to stain for GLI1 as compared with high-grade tumors." (PMID 37964226, 2023). "Moreover, non–muscle-invasive bladder tumors expressing GLI1 were less likely to recur than those in which GLI1 was absent." (PMID 37964226, 2023).
urothelial carcinoma (1 paper, 2023). A malignant neoplasm derived from the transitional epithelium of the urinary tract (urinary bladder, ureter, urethra, or renal pelvis). "As per findings of a few studies, dysregulation of SHH ligand or one of its downstream mediators, for instance, PTCH1, SMO, or GLI1, has been linked to urothelial carcinoma initiation and progression and in modulating cancer stem cell activities." (PMID 37069207, 2023).
Uterine leiomyoma (1 paper, 2020). The presence of a leiomyoma of the uterus. "Seven cases diagnosed as LG-ESS were reclassified either as HG-ESS with BCOR rearrangement (n = 2), malignant epithelioid neoplasm with GLI1 rearrangement (n = 2), NCOA fusion-positive uterine tumors (n = 2) or uterine leiomyoma (n = 1)." (PMID 32933053, 2020).
Wilms tumor (1 paper, 2008). An embryonal neoplasm characterized by the presence of epithelial, mesenchymal, and blastema components. "Important for their relation to Wilm's Tumor, several of these TFs have previously been implicated in cancer (NANOG, GLI1, E2F1, POU5F1/OCT4, SPI-1, YY-1, GATA1, and C/EBP-β)." (PMID 18564415, 2008).
tumor (669 papers, 2006 to 2026). "In T-ALL patients with central nervous system metastasis Gli1 deficiency has been observed: tumor spread was promoted by Hh activation, triggered via the Akt/FOCX1/Gli2 axis." (PMID 39996741, 2025). "In the context of Hh signaling, miR-301a modulates pathway activity through its regulation of Gli1, which is essential for downstream signal transduction and gene activation associated with cell proliferation and tumor growth." (PMID 39846248, 2025). "In vivo limiting dilution assay using CD133+/LGR5+ PCSC xenografts demonstrated that GD reduces tumor growth, metastasis, and stemness associated with PCSCs by downregulating the expression of Shh and Gli1." (PMID 41599621, 2025). "Coherently, it has been demonstrated that high levels of GLI1, the main effector of HH signaling, are associated to higher incidence of tumor relapse in 5-FU-treated CRC patients." (PMID 40640948, 2025). "Our results provide novel insights into the molecular mechanisms underlying the involvement of GLI1/2/3 in tumor development and their impact on the immune microenvironment." (PMID 38498906, 2024). "The sonic hedgehog (Shh)/glioma-associated oncogene homolog 1 (Gli1) signaling pathway is known to be aberrantly activated in various human neoplasms, playing a critical role in tumor development and progression." (PMID 38794148, 2024). "Loss of GLI1, in turn, leads to a suppression of the Hh pathway and a significant reduction in Hh-dependent tumor cell proliferation." (PMID 39695131, 2024). "Research has also indicated that positive immunohistochemical staining for CD44, Shh, and Gli1 proteins was associated with larger tumour sizes, more severe gross and histological types, and higher TNM stages." (PMID 38920995, 2024). "Betulinic acid caused a more regional expression of GLI1 leaving large tumor areas unstained compared to homogeneously stained regions of GLI1 in tumor tissues of untreated mice." (PMID 36615262, 2022). "In HCC, the high expression of SMO and GLI1, members of the Hedgehog signalling pathway, directly triggers the formation of larger tumours and is significantly associated with recurrence." (PMID 35459884, 2022). "The IHC results showed that the P. acnes strain significantly increased the expression of Gli1, whose high expression was thought to be associated with tumour progression." (PMID 36358596, 2022). "We identified two GLI1 variants found in multiple patient-derived tumor samples, R100C and S105F, that substantially weakened SUFU binding, and have been highly conserved throughout animal evolution." (PMID 35831023, 2022). "We demonstrate that loss of AR in stromal Shh-responsive Gli1-lineage cells diminishes prostate epithelial oncogenesis and tumor development." (PMID 36323713, 2022). "A preclinical trial has shown that targeting GLI1 exhibits an anti-tumor effect and efficiently overcomes the tumor resistance caused by SMO inhibitors in breast cancers." (PMID 35805056, 2022). "Here, we demonstrate that loss of AR in stromal sonic-hedgehog Gli1-lineage cells diminishes prostate epithelial oncogenesis and tumor development using in vivo assays and mouse models." (PMID 36323713, 2022). "To begin to investigate these possibilities, we chose 20 tumor-derived single-amino-acid substitution mutations in the region spanning residues 80–130 of GLI1, and used site-directed mutagenesis to introduce them into GLI11-232." (PMID 35831023, 2022). "In GC, Gli-1 expression has been reported to be positively linked to a more aggressive tumor phenotype." (PMID 33639931, 2021). "Elevated GLI1 expression levels are associated with improved survival in NB patients and GLI1 overexpression exerts tumor-suppressive traits in cultured NB cells." (PMID 33921042, 2021).
tumor (continued). "LATS1 suppressed the expression of glioma-associated oncogene-1 (Gli1), and LATS1's tumor-suppressive actions in CRC are dependent on Gli1." (PMID 35003351, 2021). "Glioma-associated transcription factor-1 (GLI1) amplification was detected by targeted next-generation sequencing (NGS) in the tumor tissue." (PMID 34778066, 2021). "Abnormal activation of sonic hedgehog (Shh)/Glioma-associated oncogene homolog I (Gli1) pathway occurs in human neoplasms." (PMID 34026649, 2021). "Compared to Gli1CreERT2;Smofl+ mice that retained one functional Smo allele and hence the capacity to activate Hh signaling, mice with complete loss of Smo in Gli1-expressing cells had an increased tumor burden." (PMID 33498528, 2021). "Hh signaling pathway has a critical function during the EMT, angiogenesis, and tumor progression of GC through glioma-associated oncogene 1 (GLI1)." (PMID 32467737, 2020). "The miR-202-3p level is known to correlate negatively with tumor size, transcriptionally target Gli1 and inactivate the Shh signal, and has been linked to the tumorigenesis and progression of various types of human malignancies." (PMID 32764512, 2020). "As a consequence, the tumor growth-promoting feature of Cav-1-deficient PSCs is reversed through suppressing shh signaling with cyclopamine and by interfering with Gli-1 in Aspc-1 cells." (PMID 32377291, 2020). "Herein, we provide mechanistic rationale for acquired or inherent chemotherapeutic resistance to the anti-tumor effects of 5-fluorouracil (5-FU) that is linked to oncogenic GLI1 transcription activity and NBS1 overexpression." (PMID 32185127, 2020). "In conclusion, the current study illustrated that the Shh/Gli1 pathway is aberrantly activated in GC, and the overactivation of the Shh/Gli1 pathway is associated with a higher aggressive tumor phenotype and a poorer prognosis of patients with GC." (PMID 32328197, 2020). "In a TNBC cohort, increased SHH and SMO expression was associated with high histological grades, and SMO and GLI1 correlated with high tumor stages." (PMID 31027259, 2019). "Strong association was observed between expression of SHH and GLI1 in the tumor samples (r = 0.42, p < 0.0001)." (PMID 31036836, 2019). "Further complexity is added by the recent observation that Shh produced by tumor associated astrocytes promote medullobastoma growth by increasing nestin expression independently of Gli-1." (PMID 31788004, 2019). "In BCC, coincidental high expression of PTCH1 and GLI1 is only seen in tumours expressing a mutated PTCH1 allele that is ineffective at suppressing the HH pathway." (PMID 30068568, 2018). "Over expression of SHH, DHH and GLI1 were associated with cell grades in Finak dataset and also related with poorly differentiated tumours." (PMID 29329585, 2018). "Promoting Gli zinc-finger transcription factors translocate into nucleus, especially Gli1 is associated with tumor proliferation, metastasis and drug resistance." (PMID 29321573, 2018). "Glioma-associated oncogene 1 (Gli1) is a critical transcriptional factor of Sonic hedgehog pathway which has been proved to participate in the initiation and progression of tumor in mammalians." (PMID 29113369, 2017). "Aberrant activation of HH/Gli1 signaling pathway has been implicated in a fraction of GBM, and inhibiting HH/Gli1 signaling results in tumor growth suppression." (PMID 29225516, 2017). "Further analyses indicate elevated GLI1 expression is associated with an increase in tumor sphere formation, side population and cell surface markers for putative cancer stem cells." (PMID 28404967, 2017). "Overexpression of nuclear GLI-1 is linked with tumor recurrence, lymphatic metastasis and the primary tumor size of OSCC." (PMID 28708091, 2017). "Patients with chronic cholecystitis often advanced to gallbladder carcinoma; and patients whose tumor samples expressed high levels of GLI1 were associated with unfavorable survival outcomes." (PMID 26988232, 2016).